CHD4 (chromodomain helicase DNA binding protein 4)
Diseases named in the same sentence as CHD4 in open-access papers (continued):
Sharing a sentence is not in itself a finding about the gene and the disease.
breast cancer (continued). "In conclusion, our approach identifies diverse epigenetic targets as crucial oncogenes in breast cancer, suggesting in particular that CHD4 targeting can be used as an efficient strategy to arrest breast cancer progression." (PMID 27779108, 2016). "To contextually analyze the effect of CHD4 and its putative effectors in breast cancer cell cycle progression, we took advantage of a more quantitative and sensitive technique, the A.M.I.C.O." (PMID 27779108, 2016). "Among the genes identified in our screening, we deeply investigated the role of Chromodomain Helicase DNA binding Protein 4 (CHD4) in breast cancer tumorigenesis." (PMID 27779108, 2016). "Cells derived from the dissociation of spontaneously growing mammary tumors were infected using two pooled shRNAs targeting Chd4 or control scramble (SCR) shRNAs and then transplanted into syngeneic mice." (PMID 27779108, 2016). "We have fully validated the epigenetic screens in vivo and in vitro by analyzing four different hits and we have demonstrated that BAZ1B, BPTF, BRD4 and CHD4 are essential for breast cancer growth." (PMID 27779108, 2016). "In unchallenged basal breast cancer cells, CHD4 modulates chromatin accessibility." (PMID 38281186, 2024). "In this study, we measured the impacts of CHD4 depletion in MDA-MB-231 basal breast cancer cells." (PMID 38281186, 2024). "Thus, the evidence suggests that CHD4 enhances ERα transcriptional activity in ERα-positive breast cancer cells." (PMID 38292202, 2024). "CHD4 and ERα protein concentrations were strongly correlated in ERα-positive breast cancer cells." (PMID 38292202, 2024). "Our findings demonstrated that CHD4 exhibits oncogenic properties, as evidenced by its overexpression up-regulating ERα through two pathways, increasing the mRNA of ERα and decreasing its protein ubiquitin-dependent degradation in ERα-positive breast cancer." (PMID 38292202, 2024). "For instance, it was reported that upregulated hsa_circ_0006528 contributed adriamycin-resistant in breast cancer via the miR-1236-3p/CHD4 axis and circABCB10 was overexpressed in breast cancer that was involved in paclitaxel resistance through the circRNA/let-7a-5p/DUSP7 axis." (PMID 34980129, 2022). "Compelling evidence indicates that CHD4 is a biomarker of drug sensitivity in cancer cells and that pharmacological inhibition of CHD4 expression could improve clinical outcome in breast cancer patients." (PMID 33981601, 2021). "In ERBB2+ breast cancer cells, which are resistant to Trastuzumab, a monoclonal antibody anticancer treatment, the depletion of CHD4 was shown to induce the cell’s sensitivity to this antibody by reducing ERBB2 signaling, affecting the autophagy process, and decreasing cell proliferation." (PMID 34142021, 2021). "Here we assess whether CHD4 expression level is a marker of poor prognosis, and if depletion of CHD4 could impact the therapeutical approach used in breast cancer." (PMID 33981601, 2021). "Further, CHD4 depletion could increase sensitivity to trastuzumab treatment of HER2+ breast cancer cells, and CHD4 silencing improves sensitivity to cisplatin and PARP1 inhibitor in TNBC cells." (PMID 33981601, 2021). "In addition, CHD4 knockdown increased the chemosensitivity of breast cancer cells towards cisplatin and increased the sensitivity of hepatocellular carcinoma cells towards epirubicin, an antitumor antibiotic." (PMID 34142021, 2021). "CHD4 is essential for growth of multiple patient derived melanoma xenografts and for breast cancer." (PMID 33741961, 2021). "Chromodomain-helicase-DNA-binding protein 4 (CHD4) is an epigenetic regulator identified as an oncogenic element that may provide a novel therapeutic target for the treatment of breast cancer (BC)." (PMID 33981601, 2021). "The chromodomain helicase DNA-binding 4 (CHD4), a member of the nucleosome remodeling and deacetylases (NuRD) complex, has been identified as an oncogene that modulates proliferation and migration of breast cancers (BC)." (PMID 30967373, 2019).
breast cancer (continued). "Our previous data demonstrated that CHD4 knockdown could sensitize cancer cells to DNA insult drugs in breast cancer and osteosarcoma." (PMID 31438571, 2019). "We previously reported the mutation spectra for CHD4 and CHD5 in TCGA breast cancers." (PMID 28649742, 2017). "In particular, it has already been demonstrated that CHD4, together with the other subunits of the NuRD complex, is implicated in tumor progression, but up to now no data were available in breast cancer." (PMID 27779108, 2016). "It is also reported that the ablation of CHD4 causes a downregulation of PI3K protein levels, as well as decreased phosphorylation of AKT and ERK (important pro-survival and proliferation kinases), and induces p27KIP1 upregulation, simultaneously inhibiting ERBB2+ breast cancer cell proliferation." (PMID 40004553, 2025). "Knockdown of CHD4 could overcome the resistance of approved drugs in acute myeloid leukemia cells or in human epidermal growth factor receptor 2-positive patients 23, 24 and also inhibit tumor growth and increase cytotoxicity in breast cancer 24-27." (PMID 33994851, 2021). "Our study provides insight into the molecular mechanism whereby CHD4, and some of its mutants could play a role in breast cancer and suggest important implications for the biological comprehension and prognosis of breast cancer, identifying CHD4 as a novel therapeutic target for BC patients." (PMID 33981601, 2021). "Therefore, CHD4 should be considered a potential target in ERBB2+ breast cancers." (PMID 30967373, 2019). "CHD4 deficiency was shown to reduce the recruitment of homologous recombination repair factor BRCA1, and it impaired the efficiency of homologous recombination repair, which could affect the treatment of breast cancer characterized by BRCA1/BRCA2 mutations." (PMID 28649742, 2017). "Notably, CHD4 silencing significantly reduced in vivo growth (80%), confirming the role of CHD4 in growth maintenance of two different metastatic breast cancer subtypes and suggesting that CHD4 can be a potential druggable target also for the most aggressive diseases." (PMID 27779108, 2016). "However to date, the role of CHD4 in breast cancer progression has been poorly investigated." (PMID 27779108, 2016). "The abolition of CHD4 in SKBR-3 and BT474 breast cancer cells intervened in the ERBB2 signaling cascade." (PMID 40004553, 2025). "Predictions of known cancer driver genes in new cancer types include SPTA1, CHD4 and ASXL1 in colorectal cancer, FOXO3, MUC16 and ZFPM1 in breast cancers and CNTNAP2, CTNND2 and TRRAP in lung adenocarcinoma." (PMID 38890488, 2024). "To explore the range of chromatin features regulated by CHD4 in somatic cells, we depleted it in MDA-MB-231 basal breast cancer cells using shRNA followed by genome-wide analysis of chromatin accessibility using ATAC-seq." (PMID 38281186, 2024). "Among the 34 380 GATA3 peaks that we had previously defined, CHD4 signals were observed at 16 225 GATA3 peaks (47%), confirming the frequent overlap between CHD4 and GATA3 in luminal breast cancer cells." (PMID 38281186, 2024). "We and others have previously shown that epigenetic coregulators such as ZMYND8, CHD4, CARM1, TRIM24, and JMJD2C are frequently amplified or upregulated to promote breast cancer progression through their role in epigenetic reprogramming." (PMID 37655663, 2023). "Thus, CHD4 status could determine the response of BC patients to current treatments, and pharmacological inhibition or targeting of CHD4 expression could improve the clinical outcome in breast cancer patients according to breast cancer type." (PMID 33981601, 2021). "CHD4 silencing strongly stimulated PADI1 and PADI3 expression in MCF7 breast cancer cells and increased glycolysis." (PMID 33741961, 2021). "Taken together, our results suggested that elevated expression of TRPS1 nucleates CHD4/NuRD(MTA2) complex to repress ΔNp63 expression to reduce cell migration and invasion of breast cancer cells and better survival." (PMID 30563971, 2018).
breast cancer (continued). "In contrast to CHD3, the expression level of CHD4 was higher in Luminal, HER2+, and basal-like breast cancer compared with normal-like breast cancers." (PMID 28055972, 2017). "To better uncover the role of CHD4 in breast cancer maintenance, we chose the MMTV-NeuT transgenic mouse model that closely reflects some features of the aggressive human G3 breast cancer and of the human HER2 positive (+) tumors." (PMID 27779108, 2016). "To explore the role of CHD4 in patients, we used PDX models of Luminal B and Triple Negative breast cancer." (PMID 27779108, 2016). "Previous studies have observed that CHD4, subunit of NURD complex, could increased RNA polymerase II at promoters of targets to potentiate HIF-driven transcriptional programs in breast cancer." (PMID 36967443, 2023). "While it was not tested in ovarian cancer, in glioblastoma and breast cancers, it was demonstrated that knockdown of CHD4 decreases the expression of RAD51 and p21 that are tightly involved in cisplatin sensitivity." (PMID 34161330, 2021). "These authors suggested that the pharmacological inhibition of CHD4 might improve the treatment of TNBC and could also overcome resistance to approved drugs in the case of HER2+ breast cancers." (PMID 33981601, 2021). "However, another study indicated that CHD4 was a pan-cancer biomarker to another HDAC inhibitor sensitivity in colon and breast cancer cells." (PMID 33994851, 2021). "We further analyzed the expression data of 1762 breast cancers retrieved from GEO and found a statistically significant negative correlation of the expression between TRPS1 and TP63 (r = −0.3387, p < 0.001) and between CHD4 and TP63 (r = −0.3751, p < 0.001)." (PMID 30563971, 2018). "It is also found that CHD4 regulates SRY-box 2 (SOX2: regulator of stem cell pluripotency and has a role in the function of cancer stem cells, CSCs) transcription through TRPS1 (GATA-type transcription factor that promotes angiogenesis) in luminal breast cancer." (PMID 40004553, 2025). "Conclusions were that CHD4 coactivates HIF to promote breast tumor growth, and that different mRNAs were also up-regulated in human breast tumors (ZMYND8, KDM4C (JMJD2C), CDK8, CREBBP (CBP), KAT), suggesting the heterogeneity of epigenetic regulation of HIF in breast cancer." (PMID 33981601, 2021). "Thus, some authors have suggested that CHD4 depletion (via low CHD4 mRNA expression) might modulate the response to cisplatin in ovarian and BRCA2 breast cancers." (PMID 33981601, 2021). "We demonstrated that CHD4 silencing inhibits tumor growth in vivo and proliferation in vitro by strongly reducing cell cycle progression in xenografts of MCF10DCIS.com cells, in transgenic, HER2-activated, mouse model and in patient-derived xenografts (PDX) of breast cancer." (PMID 27779108, 2016).
endometrial cancer (17 papers, 2015 to 2025). Primary or metastatic malignant neoplasm involving the endometrium (mucous membrane that lines the endometrial cavity). "Somatic mutations in CHD4 are found in the endometria of healthy women and those with endometrial cancer." (PMID 41417740, 2025). "CHD4 has been shown to have tumor suppressive properties in human endometrial carcinoma cell lines, with CHD4 loss leading to increased invasion and stemness in vitro." (PMID 41417740, 2025). "The majority of CHD4 mutations in endometrial carcinoma are missense mutations and are thought to lead to reduced or loss of CHD4 function." (PMID 41417740, 2025). "To this end, we generated a conditional Chd4 floxed allele, which, when combined with BAC-Sprr2f-Cre, targets Chd4 knockout to the endometrial epithelium, the proposed cell of origin for endometrial carcinoma." (PMID 41417740, 2025). "CHD4 is the predominant chromatin remodeling gene mutated or altered in an aggressive form of endometrial carcinoma known as uterine serous carcinoma." (PMID 41417740, 2025). "Loss of CHD4 function promotes endometrial cancer stemness by activating the TGF-β pathway while suppressing stemness maintenance in papillary thyroid carcinoma." (PMID 38268032, 2024). "For instance, CHD4 depletion and CHD4 mutations promote endometrial cancer stemness by activating TGF-beta signaling." (PMID 38268032, 2024). "CHD4 homologues are found in most complex organisms and CHD4 function in humans is linked to many diseases, including acute myeloid leukaemia, rhabdomyosarcoma, endometrial carcinoma, and neurodevelopmental disorders." (PMID 39221830, 2024). "In endometrial cancer, CHD4 is involved in the progression from endometrial atypical hyperplasia (AH) to uterine endometrioid carcinoma (EC), and mutations in CHD4 can promote endometrial tumorigenesis." (PMID 36681835, 2023). "In vivo tumorigenecity studies in endometrial cancer have revealed R975H and R1162W as mutations that lead to CHD4 loss-of-function." (PMID 33981601, 2021). "In endometrial cancer, CHD4 mutation has been shown to promote tumorigenesis via TGF-β signaling pathway." (PMID 33419089, 2021). "In the last decade, large-scale exome sequencing has revealed a CHD4 gene mutation frequency of 17–20% in different types of endometrial cancers, and the gene is also frequently mutated in different types of gynecological cancers." (PMID 33981601, 2021). "CHD4 expression is also associated with cancer stemness in hepatocellular carcinoma, glioblastoma and endometrial cancer." (PMID 33419089, 2021). "CHD4 somatic variants are also involved in uterine serous carcinoma, an aggressive endometrial cancer." (PMID 31238879, 2019). "In endometrial cancer, CHD4 is one of the most frequently mutated tumor suppressor genes and typically sustains missense mutations (instead of deletions)." (PMID 32577620, 2019). "We previously reported that CHD4 depletion and CHD4 mutations promote endometrial cancer stemness by activating TGF-beta signaling." (PMID 32577620, 2019). "CHD4 missense mutations identified in endometrial cancer are enriched in the ATPase domain (24 missense mutations affecting 19 residues)." (PMID 29844320, 2018). "The majority of missense mutations identified in endometrial cancer map to the three domains of CHD4: the PHD fingers, the double chromodomains and the ATPase domain." (PMID 29844320, 2018). "It is clear that the majority of CHD4 mutations identified in endometrial cancers negatively impact ATPase and/or remodelling activity." (PMID 29844320, 2018). "Endometrial carcinoma of the serous type has the highest incidence of CHD4 mutations (17%) but CHD4 mutations are also present in mixed histology, endometrioid and clear cell carcinoma." (PMID 29844320, 2018). "Here, we characterise the effects of CHD4 mutations identified in endometrial carcinoma on the remodelling properties of dMi-2, the highly conserved Drosophila homologue of CHD4." (PMID 29844320, 2018).
endometrial cancer (continued). "CHD4 is mutated in endometrial carcinoma, with most mutations leading to loss of function." (PMID 40501592, 2025). "CHD4 is mutated in endometrial carcinoma, with most mutations resulting in loss of function." (PMID 41417740, 2025). "We recently showed that two point mutations of CHD4 (R975H and R1162W) in ATPase domain in endometrial cancer destabilized the CHD4 protein and consequently diminished the function of CHD4, which induces a cancer stem cell phenotype to promote cancer progression." (PMID 32577620, 2019). "R1162 is the most frequently mutated CHD4 residue in endometrial carcinoma." (PMID 29844320, 2018). "Knowing that endometrial carcinomas and other pathologies of the endometrium, including endometrial hyperplasia and endometriosis, are thought to arise from the endometrial epithelium, we created an endometrial epithelial-specific mouse model of conditional CHD4 loss." (PMID 41417740, 2025). "In addition to ARID1A, it should be noted that CHD4 mutations leading to nucleosome remodeling defects are also frequent in endometrial cancer and may lead to de-repression of similar target genes." (PMID 36153585, 2022). "Nineteen of the 36 potentially harmful mutations located in the ATPase/helicase functional domain of CHD4 are highly conserved residues and have been also found in endometrial cancer." (PMID 33981601, 2021). "It is conceivable that a reduction of overall CHD4 activity in endometrial cancer cells contributes to cancerogenesis." (PMID 29844320, 2018). "Whole exome sequencing of serous uterine tumors, a highly aggressive form of endometrial cancer, identified Chd4 as one of the proteins containing high frequencies of somatic mutations." (PMID 26075616, 2015). "A recent report suggested that knockdown of CHD4 or its mutations (R975H or R1162W) is implemented with increased expressions of TGFB1 and CD133 (cancer stem cell marker), followed by the progression of uterine (endometrial) cancer." (PMID 40004553, 2025). "In endometrial carcinoma, CHD4 has been reported to have both tumor suppressive and oncogenic activity, supporting the notion that CHD4 gene dosage may be key to understanding the context-dependent CHD4 activity." (PMID 41417740, 2025). "It was found that both mutations can reduce the half-life of CHD4 protein and inactivate CHD4 protein to promote the phenotype of CSCs through the TGF-β/CD133 pathway, expand the CSCs population, and enhance the progression of endometrial cancer." (PMID 33898430, 2021). "Moreover, CHD4 has been demonstrated to be specific to endometrial cancer." (PMID 38539419, 2024). "Therefore, unlike in other cancers, CHD4 acts as a tumor suppressor gene in endometrial cancer via modulation of the TGFB1/CD133 pathway." (PMID 40004553, 2025).